S100Z (S100 calcium binding protein Z)
Synonyms: Gm625; S100-zeta
Tractability: No criterion of Open Targets' tractability assessment is met for any kind of drug.
Gene: Protein-coding gene on chromosome 5 (76,850,001 to 76,921,650, forward strand). Ensembl gene ENSG00000171643.
Subcellular location (Human Protein Atlas): Centrosome; Cytosol; Nucleoplasm
Gene Ontology:
Molecular function: calcium ion binding; protein binding; protein homodimerization activity; calcium-dependent protein binding; identical protein binding
Genetic constraint (gnomAD): Loss-of-function variants: 3 observed, 2.95 expected, observed/expected ratio (o/e) 1.02, 90% interval 0.44 to 1.86. That is too few expected variants to judge how well the gene tolerates losing a copy. Missense variants: 41 observed, 30.37 expected, observed/expected ratio (o/e) 1.35, 90% interval 1.05 to 1.74. Synonymous variants: 14 observed, 12.45 expected, observed/expected ratio (o/e) 1.12, 90% interval 0.74 to 1.72.
Homologues: Orthologues: chimpanzee S100Z (99% identical), guinea pig S100Z (93% identical), mouse S100z (90% identical), rat S100z (90% identical), pig S100Z (87% identical), tropical clawed frog s100z (76% identical), zebrafish s100z (68% identical). Paralogues in human: S100A1 (55% identical), S100P (49% identical), S100A4 (44% identical), S100B (41% identical), S100A10 (40% identical), S100A5 (40% identical), S100A2 (39% identical), S100A12 (37% identical), S100A3 (35% identical), S100A6 (35% identical), S100A9 (33% identical), S100A11 (31% identical), and 9 more.
Diseases named in the same sentence as S100Z in open-access papers:
S100Z is named in the same sentence as 12 diseases in open-access papers, as found by Europe PMC text mining. Sharing a sentence is not in itself a finding about the gene and the disease. The quoted sentences say what the papers report.
breast carcinoma (2 papers, 2017 to 2019). "Elevated mRNA levels of S100Z have been associated with both shorter overall survival and opposite, longer, relapse-free survival and distant metastasis-free survival in breast cancer patients." (PMID 31344832, 2019). "S100A10 and S100Z mRNA expression were associated with lower OS in basal-like breast cancer." (PMID 28051137, 2017).
diabetes (2 papers, 2022 to 2025). "The S100 family member S100z was identified in our previous study as the most striking gene to be causal for the diabetes QTL Nidd13/NZO by affecting islet cell proliferation as well as apoptosis when overexpressed in mouse insulinoma (MIN6) cells." (PMID 40468979, 2025). "In summary, with the current study, we identified the calcium-binding protein S100z as the most striking gene to be causal for the diabetes QTL Nidd13/NZO by affecting β-cell proliferation as well as apoptosis and is thereby regulating glucose homeostasis." (PMID 35328627, 2022). "In summary, we define S100z as the most striking gene to be causal for the diabetes QTL Nidd13/NZO by affecting β-cell proliferation and apoptosis." (PMID 35328627, 2022). "In the present study, we have shown that the family member S100z, located within the diabetes QTL Nidd13/NZO, is involved in β-cell proliferation as well as apoptosis." (PMID 35328627, 2022). "Thus, S100z is an entirely novel diabetes gene regulating islet cell function." (PMID 35328627, 2022).
ovarian carcinoma (1 paper, 2018). A malignant neoplasm originating from the surface ovarian epithelium. "While, the S100A12 (HR = 0.56, 95%CI: 0.41–0.78, P = 0.0043), S100A13 (HR = 0.73, 95%CI: 0.53–1.01, P = 0.058) and S100Z (HR = 0.6, 95%CI: 0.37–0.96, P = 0.032) expression predicted better prognosis in grade II ovarian cancer patients." (PMID 30558666, 2018).
tumor (3 papers, 2018 to 2023). "Apart from SAR1B, ZBTB33, STYX, KLRC3, and S100Z, there were significant differences in the other 10 DEGs levels in the tumor-stroma crosstalk." (PMID 30519576, 2018). "Although the expression of S100Z was not significantly different between tumor marginal tissues and tumor core tissues, the expression level was significantly increased in tumor core tissues and tumor marginal tissues relative to paracancerous tissues." (PMID 35592707, 2022). "As S100A5, S100A7, S100A7A, S100Z, TCHHL1, and S100G are ubiquitously expressed at low levels in both tumor and paratumor samples, they were not included in the following analyses." (PMID 37133437, 2023).
cancer (2 papers, 2020 to 2024). A tumor composed of atypical neoplastic, often pleomorphic cells that invade other tissues. "Interestingly, the landscape of CNV is marginally variable, while almost all S100s amplification could be observed in certain cancers, and S100Z was showed deletion in several cancers." (PMID 38684596, 2024). "Based on the Oncomine database, there are no obvious distinctions in S100A1, S100A4, S100A5, S100A6, and S100A13 expressions between cancer tissues and normal colon mucosa, and S100A7, S100A12, and S100Z are slightly overexpressed in CRC tissues." (PMID 33294444, 2020).
adenocarcinoma (1 paper, 2018). A common cancer characterized by the presence of malignant glandular cells. "S100G (HR = 1.29, 95% CI: 1.03–1.63, and p = 0.0290) and S100Z (HR = 0.91, 95% CI: 0.71–1.16, and p = 0.4300) were not significantly related to prognosis in adenocarcinoma and expression of the other 17 S100 members correlated with worse OS." (PMID 29607329, 2018).
S100Z also shares sentences with these, for which no sentence is quoted: ameloblastoma (1 paper); endometrial carcinoma (1); glioma (1); insulinoma (1); oral squamous cell carcinoma (1); pancreatic cancer (1).